LEP (leptin)
Diseases named in the same sentence as LEP in open-access papers (continued):
Sharing a sentence is not in itself a finding about the gene and the disease.
adenoma (10 papers, 2010 to 2025). A neoplasm arising from the epithelium. "Tissue microarray analysis showed that leptin was gradually expressed during the normal-adenoma-adenocarcinoma sequence, suggesting an association between leptin and colorectal carcinogenesis." (PMID 33167521, 2020). "Individuals in the highest quartile of leptin concentrations had increased adenoma risk compared with those in the lowest quartile in men (3.67-fold, 95% CI = 1.30–10.3, p = 0.01), but not in women." (PMID 30279628, 2018). "High serum leptin was also correlated with a decreased risk of recurrent adenoma." (PMID 24465801, 2014). "Serum concentrations of adiponectin (pg/ml), IGF-1 (ng/ml), TNF-α (pg/ml), and leptin (pg/ml) were significantly higher in adenoma group." (PMID 29593647, 2018). "Additional and larger studies of leptin and adenoma are needed to obtain more representative and stable estimates and to examine differences within subgroups including sex and race." (PMID 25197277, 2014). "Adipocytes secrete molecules such as adiponectin, CTRP1, leptin, osteopontin, and resistin, which may stimulate aldosterone production in addition to the aldosterone-secreting adenoma." (PMID 37452142, 2023). "Median serum leptin concentration in adenoma cases was 16.4 vs. 13.9 in controls (P = 0.048)." (PMID 29593647, 2018). "More recently, a case-control study of Japanese men and women reported a statistically significant association between adenoma risk and circulating leptin levels among men, but not women." (PMID 25197277, 2014). "Furthermore, this research suggests that high serum concentrations of leptin (>9 ng/ml), IP-10 (>362.6 pg/ml) and TNF-α (>5.9 pg/ml) could also be used to identify individuals at increased risk for colorectal polyp formation and presence of adenoma." (PMID 24465801, 2014). "Leptin and adiponectin did not mediate the waist-to-hip ratio (WHR) adenoma association in either group (all Sobel P values >0.27)." (PMID 25197277, 2014).
alcoholism (10 papers, 2012 to 2026). "Other potential targets for microbiome therapeutic strategies include gastrointestinal hormones implicated in alcoholism such as ghrelin, leptin, and GLP-1, as well as neurotransmitters implicated in the alcoholic GBA, such as serotonin and dopamine." (PMID 35310839, 2022). "There is growing evidence that appetite-regulating peptides such as leptin and ghrelin are altered in alcoholism." (PMID 38951515, 2024). "Accordingly, patients with alcoholism present higher liver fat levels but show lower total fat mass what affects leptin circulating levels." (PMID 33316927, 2020). "By way of illustration, it has been proved that the exogenous administration of leptin in alcohol-induced liver damaged mice results in a reduction of hepatic lipid levels, independently of changes in body weight and food intake." (PMID 33316927, 2020). "Increasing evidence supports the role of appetite-regulating pathways, including ghrelin and leptin, in alcoholism." (PMID 26418274, 2015). "Serum leptin levels have been reported to be altered in alcohol-dependent patients." (PMID 34526917, 2021). "The goal of this study was to evaluate the effect of transcutaneous auricular vagus nerve stimulation (taVNS) on PAWS and plasma brain-derived neurotrophic factor (BDNF), interleukin-6 (IL-6), tumor necrosis factor-α (TNF-α), and leptin levels in patients with alcohol dependency." (PMID 34526917, 2021). "Thus, the effect of taVNS on plasma leptin levels in patients with alcohol dependency was investigated." (PMID 34526917, 2021). "The present study aimed to investigate whether endotoxin lipopolysaccharides (LPS) and high-mobility group box-1 protein (HMGB1), a key inflammatory mediator, as well as the metabolic fat mass hormone leptin, are reliable biomarkers for the estimation of alcohol dependence and abstinence." (PMID 42198566, 2026). "Plasma leptin concentrations were positively correlated with the plasma IL-6, CRP, and TNF-α levels in the present study, which suggests that the role of leptin as a marker of addiction in alcohol-dependent patients may be related to the changes in inflammatory cytokines." (PMID 32265847, 2020). "Additionally, experimental examining the role of leptin in the context of alcohol dependence would be highly valuable to better ascertain the role of leptin in the management of alcohol consumption, i.e. in ob/ob or db/db mice subjected to high and low level alcohol." (PMID 22808013, 2012). "Comparison of leptin, leptin/BMI, nesfatin-1, nesfatin-1/BMI, inflammatory cytokines, cortisol, and BDNF levels between alcohol-dependent patients and healthy controls after 1 month of abstinence." (PMID 32265847, 2020). "Based on these findings, we hypothesized that taVNS could ameliorate PAWS in alcohol-dependent patients, the mechanism of which may be related to its regulation of plasma BDNF, IL-6, TNF-α, and leptin levels." (PMID 34526917, 2021). "The goal of this study was to determine whether the plasma leptin, nesfatin-1, cortisol, brain-derived neurotrophic factor (BDNF), and inflammatory cytokines could be used as potential biomarkers for the degree of craving in the alcohol-dependent patients after 1 month of abstinence." (PMID 32265847, 2020). "However, no studies have been conducted on the relationship between leptin and PAWS in patients with alcohol dependency." (PMID 34526917, 2021).
bipolar disorder (10 papers, 2015 to 2025). A disorder of the brain that causes unusual shifts in mood, energy, activity levels and the ability to carry out day-to-day tasks. "This information could have contributed to further understand the relationship between ghrelin and leptin in bipolar disorders." (PMID 35313855, 2022). "Lower plasma leptin levels were observed in patients with bipolar disorder." (PMID 36077028, 2022). "There is however evidence that leptin levels are not altered in bipolar disorder across the mood spectrum compared to healthy controls." (PMID 35313855, 2022). "Additional work could help clarify whether leptin signaling in the brain has a role in the therapeutic action of Li and VPA in bipolar disorder." (PMID 26171981, 2015). "The main finding of this study is that the following adipokines correlated with MS in the bipolar depression women group: visfatin, S100B, and leptin had a positive correlation, whereas adiponectin, leptin-receptor, and adiponectin/leptin ratio showed a negative correlation." (PMID 37960185, 2023). "In this study, we showed that in bipolar depression, adipokines correlated with MS in the women group: VIS, S100B, and LEP had a positive correlation, whereas ADIPO, LEP_R, and ADIPO/LEP ratio showed negative correlation." (PMID 37960185, 2023).
chronic obstructive pulmonary disease (10 papers, 2009 to 2025). A chronic and progressive lung disorder characterized by the loss of elasticity of the bronchial tree and the air sacs, destruction of the air sacs wall, thickening of the bronchial wall, and mucous accumulation in the bronchial tree. "In patients with chronic obstructive pulmonary disease (COPD), for example, increased leptin is associated with decreased Treg cells in the lung due to inhibition of T-cell glycolysis, an essential metabolic pathway for T-cell survival and conversion into Tregs." (PMID 39439572, 2024). "Moreover, a higher level of leptin was reported in patients with acute exacerbation of chronic obstructive lung disease than in participants with stable disease and healthy controls." (PMID 37111072, 2023). "Interestingly, attenuated leptin/leptin R expression has also been observed in smokers and patients of chronic obstructive pulmonary disease (COPD), a neutrophil-dominated disease." (PMID 23383125, 2013). "In a cross-sectional study, leptin levels in male patients with chronic obstructive pulmonary disease (COPD) directly correlated with BMD." (PMID 40076690, 2025). "In patients with chronic obstructive pulmonary disease, BMD was also negatively related with leptin levels." (PMID 40076690, 2025).
gallbladder cancer (10 papers, 2018 to 2026). "Findings in human gallbladder cancer suggested the requirement of leptin-leptin receptor signaling axis activation in cancer progression because leptin increased cell proliferation via the leptin receptor." (PMID 33799880, 2021). "Both leptin and ObR are localized throughout the cytoplasm of luminal and glandular epithelial cells in the canine gallbladder and in human gallbladder cancer tissues and cell lines." (PMID 33167521, 2020). "In human gallbladder cancer, the experiment result also demonstrated the function of leptin in promoting cell proliferation through leptin receptor (OB-Rb), revealing the requirement of leptin receptor in leptin-dependent cancer progression." (PMID 29682217, 2018). "Moreover, exosomes from gallbladder cancer cells containing high leptin levels promote M2 macrophage polarization via STAT3 signaling and enhance gallbladder cancer cell invasion and migration." (PMID 39737074, 2024). "EVs from gallbladder cancer (GBC) harbor leptin and possess the capacity to upregulate leptin levels in TAMs." (PMID 38087360, 2023). "Leptin and its receptor LEPR promote the proliferation and metastasis of gallbladder carcinoma, which may participate in the regulation of MMPs and the VEGF family through the SOCS3/JAK2/STAT3 pathways." (PMID 33397392, 2021). "Moreover, no study has evaluated serum leptin levels and their correlation with clinicopathological characteristics and serum tumour markers in gallbladder cancer (GBC)." (PMID 37378223, 2023).
Immunodeficiency (10 papers, 2009 to 2023). Failure of the immune system to protect the body adequately from infection, due to the absence or insufficiency of some component process or substance. "Mice lacking leptin (ob/ob) or its receptor (db/db) expression show immune deficiencies suggesting a direct role of the leptin signaling on the immune system." (PMID 33994930, 2021). "Previous reports have confirmed that leptin (acts via leptin receptor) is negatively correlated with the production of regulatory T cells and hence associated with immune deficiency." (PMID 29503661, 2018). "Therefore, the elevated expression of leptin/leptin receptor in EMS prompts immune deficiency which may induce MS." (PMID 29503661, 2018). "Altogether, these findings suggest that dietary restriction and intensive exercise may cause suppressed peripheral T-lymphocyte proliferation and predominant TH2 helper cell response leading to immunodeficiency through reduction in leptin levels." (PMID 31134054, 2019). "Indeed, both, animals and humans, with defect in the leptin functions, present features of immunodeficiency, including thymic atrophy." (PMID 23675529, 2013). "Complete lack of leptin activity is associated with immune deficiencies in both mice and humans, e.g. suppression of T-cells." (PMID 19865485, 2009).
neuropathy (10 papers, 2015 to 2025). A disorder affecting the nervous system that manifests with pain, tingling, numbness, and/or muscle weakness. "To date, most research into T2DM neuropathy involves rodent models with metabolic disturbance, e.g., mice with a leptin deficiency (Ob/Ob mice)." (PMID 36917177, 2023). "Considering the inhibitory effect of low serum leptin levels on the sympathetic system associated with its impairment that occurs during the evolution of neuropathy itself, these patients present an even more favorable scenario for the development of the most severe types of CAN." (PMID 29329523, 2018). "An increased level of leptin can also affect the incidence of neuropathy." (PMID 41239264, 2025). "Thus, the presence of neuropathy may not sufficiently explain why leptin is significantly associated with HRV only in diabetic patients." (PMID 26338087, 2015). "In our hand, plasma leptin and HRV were not significantly different between diabetic patients with and without neuropathy." (PMID 26338087, 2015). "Plasma leptin (0.83 ± 0.41 vs. 0.79 ± 0.42, p = 0.610), SDNN (2.00 ± 0.13 vs. 2.04 ± 0.14, p = 0.165), and SDANN5 (1.96 ± 0.13 vs. 1.99 ± 0.14, p = 0.183) were not significantly different when compared between diabetic patients with (n = 48) and without (n = 52) neuropathy." (PMID 26338087, 2015).
ovarian dysfunction (10 papers, 2021 to 2025). The inability of the ovaries to function. "Some studies report that low levels of leptin are associated with ovarian failure, granulosa cell apoptosis, and gonadal function loss." (PMID 36379980, 2022). "In fact, PTPN2 has also been associated with the establishment of leptin resistance at central level and, therefore, appears to be an important candidate in the pathophysiology of ovarian failure in obese mothers." (PMID 33924072, 2021). "Leptin resistance was thought to be involved in the regulation of reproductive function through the HPO axis, causing ovarian dysfunction, and some studies have suggested that LP is related to the occurrence of PCOS." (PMID 34422044, 2021). "Hence, the disruption of ovarian leptin signalling was shown to contribute to the pathophysiology of ovarian failure in obese females, affecting transcriptional programmes in the gamete and somatic cells." (PMID 36855701, 2022). "Additionally, although the role of hyperleptinemia in ovarian dysfunction is discussed, the lack of direct measurement of leptin and 17β-estradiol concentrations limits the causal interpretation of this finding." (PMID 41471698, 2025).
respiratory infections (10 papers, 2011 to 2022). "More recently, a significant association between high plasma leptin levels and risk of severe respiratory infections was found in a cohort of ambulatory patients, independent on BMI and other risk factors." (PMID 35002761, 2021). "Individuals with this leptin defect also exhibited greater susceptibility to respiratory infections." (PMID 24722122, 2014). "Additionally, LEPR deficient mouse exhibits increased susceptibility to respiratory infections suggesting a leptin requirement in the pulmonary innate and adaptive immune response to infection." (PMID 36589459, 2022). "Furthermore, leptin appears to be protective against respiratory infections." (PMID 35002761, 2021). "In the acute phase, leptin is co-produced together with the main inflammatory interleukins (IL), IL-6, IL-1, and tumor necrosis factor-α (TNF-α), and acts on the sense of hunger and on the immune response, especially in respiratory infections." (PMID 32630032, 2020).
allergic rhinitis (9 papers, 2018 to 2024). Inflammation of the nasal mucous membranes caused by an IgE-mediated response to external allergens. "Recent studies suggest that leptin is involved in Th2 response in allergic rhinitis (AR)." (PMID 32214904, 2020). "In allergic rhinitis, upregulated SPP1 expression induced by leptin facilitates Th2 inflammation, and this process is mediated by α4 integrin and PI3K/Akt pathway." (PMID 31281837, 2019).
Allergy (9 papers, 2013 to 2023). An allergy is an immune response or reaction to substances that are usually not harmful. "IgE, eosinophil percentage, serum cytokine and leptin concentrations were studied as potential biological factors with a role in the associations found between weight status and allergy incidence and between sleep recommendation compliance and allergy incidence." (PMID 24405509, 2014). "Adipose tissue synthesizes and secretes a variety of cytokines and adipokines such as IL-6, TNF, TGF-β, and leptin that drive hypoinflammatory responses and have been proven to contribute to the pathogenesis of allergy." (PMID 35855823, 2022). "Therefore, they propose the supporting function of leptin on distinct T cell subsets is dependent on the skewing conditions, leading to a leptin-dependent enhancement of a type 2 response in the context of allergy." (PMID 35844529, 2022). "Leptin also has a role in both skin and allergic diseases very related to AD." (PMID 34827640, 2021). "More recently, leptin was shown to induce survival, migration, degranulation, and Th2 cytokine synthesis of human basophils, suggesting its emerging immunoregulatory role in allergic reactions." (PMID 23383125, 2013). "Therefore, in the present study, high dose of leptin should negatively impact the prognostic of allergic diseases due to the ability of this adipokine in reducing functional Treg/Tr-1 and TFR cells, CD4 T cell subset implicated in controlling Th2/Th9 and TFH2/TFH13 axis respectively." (PMID 37954580, 2023). "IgE and leptin differed between adolescents with and without allergy symptoms." (PMID 24405509, 2014).
colorectal adenoma (9 papers, 2010 to 2023). An adenoma that arises from the colon or rectum. "The association between circulating leptin and colorectal adenomas has been investigated in three epidemiologic studies." (PMID 25197277, 2014). "An association between serum leptin concentration and colorectal adenoma has been previously reported." (PMID 24465801, 2014). "Epidemiological and clinical researches had indicated that altered concentrations of leptin and adipokine might lead to the presence of colorectal adenoma and carcinoma." (PMID 30359431, 2018). "The potential role of adiponectin, leptin, IGF-1, and tumor necrosis factor alpha (TNF-α) as biomarkers in colorectal adenoma is not clear." (PMID 29593647, 2018).
Hashimoto thyroiditis (9 papers, 2018 to 2025). An autoimmune disorder caused by the production of autoantibodies against thyroid tissue. "The relationship between clinical, biochemical, and hormonal parameters and leptin serum concentration in Hashimoto thyroiditis patients and the control group." (PMID 34393994, 2021). "Until now, little is known about the role of leptin in the pathogenesis of Hashimoto’s thyroiditis." (PMID 36339447, 2022). "The leptin signaling pathway was inhibited by injection of the leptin receptor antagonist Allo-aca to investigate the relationship between leptin and the pathogenesis of Hashimoto’s thyroiditis." (PMID 36339447, 2022). "Interfering with the leptin signaling pathway may be a novel new approach to treat treating and ameliorating Hashimoto’s thyroiditis." (PMID 36339447, 2022). "Therefore, intervening leptin signaling pathway may be a new approach to treat or improve Hashimoto’s thyroiditis." (PMID 36339447, 2022). "Studies have found that serum leptin levels are slightly higher in patients with Hashimoto’s thyroiditis than in the normal group, but it is not statistically significant." (PMID 36339447, 2022). "It has been reported that serum leptin level is increased in Hashimoto’s thyroiditis, but other studies have not shown any difference." (PMID 36339447, 2022).
hypercortisolemia (9 papers, 2012 to 2025). "The mechanisms underlying the disruption of the HPG axis in chronic undernutrition include low leptin levels and hypercortisolemia due to chronic stress." (PMID 41030740, 2025). "Hypercortisolemia has been reported to interfere further with leptin’s interaction with its receptor resulting in central leptin resistance in them." (PMID 22992416, 2012). "Additionally, psychological stress can contribute to hypercortisolism, altered secretion of appetite hormones like leptin and ghrelin, and increased fat accumulation." (PMID 40262556, 2025). "However in patients with Cushing's disease, characterised by pituitary or adrenal adenoma, hypercortisolemia, and disrupted cortisol rhythms, leptin levels are highly independent of adiposity, and removal of the tumour usually results in lowered levels of both cortisol and leptin." (PMID 26000016, 2015).